INS (insulin)
Diseases named in the same sentence as INS in open-access papers (continued):
Sharing a sentence is not in itself a finding about the gene and the disease.
neuropathy (continued). "As the insulin-providing strategy was detrimental to most neurophysiological functions, the impact of GC on the neuropathy outcomes should be assessed with careful attention to treatment strategies." (PMID 29545773, 2018). "We also found that metformin-treated patients had a higher eGFR-MDRD and were younger, less likely to be taking insulin and to have neuropathy, when compared with metformin-free patients." (PMID 28202017, 2017). "Recently, additional biomarkers of neuropathy outside of peripheral nerves in the limbs have been improved by insulin." (PMID 28066166, 2016). "As expected, subjects with T2DM had worse sudomotor and cardiac autonomic function together with worse neuropathy impairment scores and other measures of somatic nerve function, glucose, A1C, insulin, C-peptide levels and HOMA indexes." (PMID 27137224, 2016). "In one cohort study, patients receiving insulin monotherapy and insulin plus metformin were twice as likely to develop neuropathy when compared to patients taking metformin alone." (PMID 24789071, 2014). "We proved the development of o-Tyr- and/or m-Tyr-induced insulin, acetylcholine, and erythropoietin resistances, which together could lead to abnormal albuminuria and neuropathy and a lower RBC count." (PMID 40227261, 2025). "At this time, neuropathy and impaired insulin secretion may still be evident, we can observe severe T2DM manifestations likewise." (PMID 40380290, 2025). "The male sex was found to be associated with DME (OR = 1.95, 95% CI: 1.02–3.73, p = 0.044), as well as duration of DM greater than 17 years (OR = 2.05, 95% CI: 1.08–3.92, p = 0.029), insulin use (OR = 2.38, 95% CI: 1.25–4.52, p = 0.008), and neuropathy (OR = 2.34, 95% CI: 1.16–4.73, p = 0.018)." (PMID 40149609, 2025). "Similarly, greater risks of fatal CHD were associated with neuropathy and CKD; higher logTG, LDL cholesterol, fasting glucose, and the use of CCB and insulin." (PMID 38263010, 2024). "In addition to CKD, neuropathy, and insulin and CCB use, higher LDL, fasting glucose, and logTG levels were associated with an increased CHD risk." (PMID 38263010, 2024). "However, the relative contribution of low insulin or high glucose levels to neuron damage and related risks of retinopathy and neuropathy still needs to be determined." (PMID 37452207, 2023). "Some patients develop early neuropathy, not necessarily associated with the use of insulin or oral hypoglycemic agents, and manifest only pain and paresthesia, which corresponds to another entity called insulin neuritis." (PMID 37223297, 2023). "Also, 66.3% of those who use insulin and oral medication had neuropathy pain compared to 33.5% of others on insulin only (P = 0.001)." (PMID 36601164, 2022). "When achieving rapid glycemic control, one study showed that insulin treatment might induce neuropathy (insulin neuritis), characterized by acute and severe pain, peripheral nerve degeneration, and autonomic dysfunction." (PMID 36611296, 2022). "First, metabolic perturbations could deteriorate bladder function through several mechanisms, such as pelvis ischemia, neuropathy, insulin resistance, and excessive succinate production." (PMID 36359236, 2022). "However, the sensory nerve conduction velocity improved significantly in honey+insulin treated neuropathy rats." (PMID 33449943, 2021). "Further experiments will show whether the combined use of insulin and α-T is able to prevent effectively neuropathies characteristic of neurodegenerative, ischemic and other brain injuries." (PMID 34769198, 2021). "Moreover, treatment-induced neuropathy (both oral hypoglycemic agents and insulin) has also been described." (PMID 32650427, 2020). "Additionally, future research would benefit from considering insulin therapy as a covariate at the time of first admission, as well as additional disease characteristics including neuropathy, retinopathy, and others." (PMID 30070989, 2018).
neuropathy (continued). "Notably, two studies comparing the progression of neuropathy in T1DM patients undergoing ITx versus those receiving intensive insulin therapy (IIT) reported differing outcomes: while neuropathy tended to improve in the IIT group, a worsening was observed in the non-transplanted T1DM controls." (PMID 41312221, 2025). "Furthermore, these data have shown that FO and ARF anti-oxidative stress potentials and insulin-secretagogue long-term anti-diabetic activities might be responsible for their antidiabetic neuropathy potentials, as seen with similar natural products." (PMID 32377229, 2020). "Moreover, later symptoms of streptozotocin neuropathy, some of which are similarly insulin reversible, have been well documented and consist of hypoalgesia, large sensory nerve fibre pathology comprising demyelination, degeneration and Schwann cell damage and regeneration." (PMID 26134846, 2015). "Nine percent of diabetic patients had neuropathy and 20% had retinopathy, 39% of the patients were on the combined oral hypoglycemic agent (OHA) and basal insulin." (PMID 37008178, 2023). "The maternal grandfather’s sister (II-5) and brother (II-6) of proband B were prescribed insulin and acarbose, respectively, their FPG levels reached 23 mmol/L at times, and both had diabetic retinopathy and neuropathy." (PMID 35992135, 2022). "The prevalence of neuropathy increased from 9 to 25% in the INT group and from 17 to 35% in the conventional CON insulin therapy group (p = 0.001) and the incidence also remained lower in the INT group (22%) relative to the CON group (28%); (p = 0.0125)." (PMID 35330052, 2022). "In this case, insulin was administered at a moderate rate (0.1U/kg/h), with no high-dose infusions, reducing the likelihood of insulin-related neuropathy." (PMID 41030450, 2025). "However, NRF2 activation has been shown to improve insulin sensitivity, enhance insulin secretion, reduce vascular inflammation, and protect against diabetic complications, including CVD, albuminuria, and neuropathy." (PMID 39857406, 2025). "Previous study reported that Insulin injection does not benefit bone regeneration, metabolism, vascularization, and neuropathy." (PMID 39687469, 2025). "Many of the processes in which VDR is involved, such as reduction of oxidative stress, neuroprotection, anti-inflammatory processes, and insulin control, are shared with SIRT1 and downregulation of both genes could contribute to the onset of neuropathy." (PMID 39976627, 2025). "Conversely, activation of NRF2 has been demonstrated to enhance insulin sensitivity, promote insulin secretion, attenuate vascular inflammation, and confer protection against diabetic complications such as CVD, albuminuria, and neuropathy." (PMID 41382274, 2025). "The observed improvements in neuropathy measures in AICAR-treated HFD-fed mice could result from its effects on lipid reduction, decreased insulin resistance, better glycemic control, and resistance to weight gain." (PMID 39795939, 2024). "The differences in the median daily dose of insulin between groups with neuropathy and without neuropathy proved to be statistically insignificant: 0.42 (IQR: 0.37–0.57) versus 0.56 (IQR: 0.44–0.63) units/kg of body weight/24 h, p = 0.08." (PMID 39664107, 2024). "Participants who developed neuropathy were more likely to be older, of the white race, belonged to the standard glycemia treatment arm, had higher levels of triglyceride, RC, BMI, but had lower levels of HDL, and were less likely to use insulin." (PMID 35668633, 2022). "In our study, diagnosis duration of more than 10 years, treatment with insulin, presence of painful neuropathy, HbA1c level and BMI did not contribute to poor sleep quality." (PMID 35564603, 2022). "The differences between the groups were not significant after adjustment for age, neuropathy, total daily insulin dose, and reason for hospitalization." (PMID 35881437, 2022).
neuropathy (continued). "After six-weeks of intervention, there was significant decrease in blood glucose and lipids in honey, insulin and honey+insulin treated neuropathy rats, when compared with no treatment group." (PMID 33449943, 2021). "In insulin-dependent and non-insulin-dependent DM animal models, the development of sensate and insensate neuropathy has been variable, with some investigators reporting one or the other or both." (PMID 24410801, 2014). "The respondents who used insulin did not confirm this fear, even if they suffered from diabetic complications (neuropathy, microangiopathy, diabetic foot syndrome)." (PMID 23251799, 2012). "In the univariate model, patients having diabetic complications including neuropathy and CKD, those with higher logTG, LDL cholesterol, fasting glucose, and those under medications such as CCB and insulin were associated with significantly greater risks of nonfatal CHD." (PMID 38263010, 2024). "We did not directly assess endothelial function or insulin resistance; both may contribute to neuropathy through impaired blood flow and metabolic dysregulation." (PMID 39439079, 2024). "However, it has been reported that low doses of insulin can improve the symptoms of neuropathy without affecting blood glucose levels, suggesting that insulin has a beneficial effect on neuropathy." (PMID 35199097, 2022). "Good metabolic control, high homogeneity of both T1D groups with and without neuropathy, and relative insulin demand could be reasons for the lack of significant differences in our analysis." (PMID 32221364, 2020). "Moreover, we demonstrated that neuropathy in female mice produced changes in lipolysis and fatty acids oxidation (FAO), as well as an enhancement of whole-body energy expenditure and higher secretion of sex hormones from AT, affecting glucose and insulin metabolism." (PMID 37817933, 2023). "Yet, it is not clear what role insulin therapy may play in the neuropathy." (PMID 26885531, 2016).
hyperandrogenism (261 papers, 2005 to 2026). Excessive secretion of androgens from the adrenal glands or gonads. "In the case of PCOS, orlistat has been associated with improved insulin sensitivity and hyperandrogenism." (PMID 41295220, 2025). "It is well-established that insulin primarily promotes androgen production in the ovary, contributing to hyperandrogenism, a hallmark feature of PCOS." (PMID 40776915, 2025). "Metformin, an insulin sensitizer, has been proven similar benefits to lifestyle interventions regarding body weight loss and even is superior in improving hyperandrogenism in PCOS women." (PMID 37347114, 2023). "In PCOS patients, ovarian cells are hyperresponsive to the stimulatory effects of insulin, thus causing ovarian hyperplasia; IR also amplifies hyperandrogenism, resulting in a disruption in the hypothalamic-pituitary-ovarian axis and aggravating PCOS." (PMID 33299379, 2020). "There are a number of genetic polymorphisms that have been associated with PCOS and point to the importance of hyperandrogenism and insulin sensitivity as potential causal mechanisms in PCOS etiology." (PMID 31367382, 2019). "Hyperandrogenism is associated with hyperinsulinemic states because insulin has the capacity to act as a co-gonadotrophin, thus stimulating ovarian androgen production." (PMID 31890686, 2019). "Studies have shown that excessive concentrations of insulin can cause hyperandrogenism by promoting ovarian and adrenal glands to secrete androgen, inhibiting SHBG synthesis in the liver." (PMID 31885557, 2019). "Because of the inverse relationship between weight and sex hormone binding globulin, Acarbose increases this globulin through weight loss and increases insulin sensitivity and decreases LH and hyperandrogenism." (PMID 27157179, 2016). "Codner and Escobar-Morreale associated the onset of hyperandrogenism with intensive insulin therapy." (PMID 27239195, 2016). "Neither of these studies tracked subjects longitudinally into young adulthood; thus, the causal relationship between disordered insulin action and a permanent, post-pubertal state of androgen excess remains unproven." (PMID 21899727, 2011). "The mechanisms through which bariatric surgery improves PCOS are undetermined: weight loss and restoring insulin sensitivity could explain the neuroregulation of the hypothalamic-pituitary axis and hyperandrogenism." (PMID 41561041, 2025). "Research has indicated that metformin treatment may lead to improvements in hormonal imbalances commonly associated with conditions such as PCOS by enhancing insulin sensitivity and indirectly decreasing biochemical hyperandrogenism." (PMID 38665260, 2024). "Even just 5% of body weight loss could meaningfully improve insulin sensitivity, hyperandrogenism, menstrual irregularity, and other reproductive and metabolic features clinically." (PMID 35663310, 2022). "Bodyweight loss may promote spontaneous ovulation by decreasing hyperandrogenism, LH levels, and insulin resistance." (PMID 36013469, 2022). "In addition to the higher prevalence of infertility in patients with PCOS due the incidence of hyperandrogenism and increase in resistance to insulin, the risk of spontaneous abortion increases in these patients in case of pregnancy." (PMID 26644787, 2015). "In addition to the clinical features of hyperandrogenism and chronic anovulation, many women are insulin resistant and at increased risk for type-2 diabetes mellitus (T2DM)." (PMID 22384174, 2012). "Furthermore, these medications may mitigate some of the reproductive health challenges associated with T2DM, such as PCOS, by improving insulin sensitivity and reducing hyperandrogenism." (PMID 40658669, 2025). "The interplay between PCOS and abdominal adiposity may be the result of a vicious circle: androgen excess promotes the abdominal deposition of body fat, and this adipose tissue facilitates androgen excess, which is linked to abnormal insulin production and release, culminating in insulin resistance." (PMID 35353297, 2022).
hyperandrogenism (continued). "Across mainly observational studies, bariatric surgery is associated with improved menstrual regularity, increased ovulation, reduced hyperandrogenism, and improved insulin sensitivity, with higher conception rates reported after substantial weight loss." (PMID 42074301, 2026). "Elevated insulin levels exacerbate hyperandrogenism by stimulating ovarian theca cells to produce excess androgens, thereby intensifying endocrine dysfunction." (PMID 41268159, 2025). "Our results are in line with these data, suggesting the stimulatory effect of insulin on PCOS-related adrenal androgen excess." (PMID 40944006, 2025). "In PCOS, hyperandrogenism arises from the interaction of ovarian theca cell dysfunction, insulin resistance, and altered hypothalamic-pituitary signalling, resulting in a chronic and systemic reproductive-metabolic imbalance." (PMID 41010046, 2025). "Our primary objective is to elucidate the specific molecular pathways through which exercise modulates the gut microbiome to improve metabolic homeostasis (notably insulin sensitivity), reduce hyperandrogenism, and mitigate inflammation in PCOS." (PMID 41234235, 2025). "Preclinical studies in rodent PCOS models consistently demonstrate improvements in insulin sensitivity, normalization of ovarian morphology, restoration of ovulation, and reduction in hyperandrogenism." (PMID 41155686, 2025). "Overall, the review indicates that, while COCs effectively manage hyperandrogenism, insulin-sensitizing agents - particularly in combination - offer superior metabolic and long-term reproductive benefits in adolescents with PCOS." (PMID 40491634, 2025). "Elevated insulin levels stimulate androgen production in the ovaries and reduce sex hormone-binding globulin (SHBG), leading to hyperandrogenism—a hallmark feature of PCOS." (PMID 40281834, 2025). "Ovulatory PCOS with hyperandrogenism and polycystic ovarian ultrasound morphology (Phenotype C) is characterized by slightly increased serum insulin, atherogenic lipids, and androgen levels, and high hirsutism scores." (PMID 40869469, 2025). "These immune cells release inflammatory cytokines, such as tumor necrosis factor-alpha (TNF-α), interleukin-6 (IL-6), and interleukin-1β (IL-1β), which impair insulin signaling and exacerbate androgen excess." (PMID 41382225, 2025). "Their altered expression patterns correspond to key pathophysiological aspects of PCOS, such as hyperandrogenism, insulin resistance, follicular arrest, and poor oocyte maturity." (PMID 40497963, 2025). "By analyzing clinical, biochemical, and metabolic data from women diagnosed between 2019 and 2024, we aim to clarify the extent to which insulin levels and vitamin D status contribute to androgen excess." (PMID 40868057, 2025). "The following sections present detailed analyses of the associations between these parameters, focusing on the relationships between vitamin D status, insulin levels, BMI, and androgen excess." (PMID 40868057, 2025). "Pharmacological therapies, such as metformin, GLP-1 receptor agonists, myoinositol, and resveratrol, are used to improve insulin sensitivity, regulate the hormonal milieu, and reduce hyperandrogenism." (PMID 40869469, 2025). "Several clinical studies have investigated potential therapeutic benefits of acupuncture for PCOS, including effects on hyperandrogenism, ovulation induction, menstrual cycle regulation, and insulin sensitivity." (PMID 40776915, 2025). "The outcomes included menstrual regularity, ovulation rates, clinical hyperandrogenism (e.g., acne, hirsutism), insulin sensitivity, body mass index, and quality of life metrics." (PMID 40491634, 2025). "Polycystic ovarian syndrome (PCOS) is a well-known metabolic disorder resulting from hyperandrogenism, ovulatory dysfunction and insulin insensitivity." (PMID 39398330, 2024).